CRP (C-reactive protein)
Diseases named in the same sentence as CRP in open-access papers (continued):
Sharing a sentence is not in itself a finding about the gene and the disease.
infection (continued). "Additionally other influencing parameters like age, weight, the Charlson index for comorbidity (CCI), the site of the infection, and laboratory infection parameters including C-reactive protein, fibrinogen, and leukocyte count were studied." (PMID 30426000, 2018). "Nonetheless, an increase in CRP levels may occur in many other situations as well as in the presence of infection, including during a normal or physiological pregnancy when levels reflect the adaptations needed to support the fetus." (PMID 30205601, 2018). "This could be largely explained by the fact that all children at risk for serious infection according to the clinical prediction rule received a POC CRP test and were therefore assigned to the 'CRP tested' group." (PMID 30354904, 2018). "Subclinical infection was detected by measuring C-reactive protein (CRP)." (PMID 30205601, 2018). "CRP, an acute-phase protein, is produced by the liver in response to injury and/or infection." (PMID 29189992, 2018). "In critically ill patients with AKI stage 2/3, suPAR is a better marker of infection than CRP." (PMID 30071826, 2018). "With the clinical validation of tools such as the AUC:EC50 for predicting antimicrobial PD in individuals using markers such as CRP, future work must now explore the role of using newer infection-related biomarkers, such as procalcitonin and CD64 for improving the accuracy of these tools." (PMID 29211877, 2018). "Interestingly, in contrast to CRP, only IG percentage was a significant predictor of severe infection." (PMID 30344287, 2018). "In six out of ten patients with increased CRP levels, a clinical relevant infection was apparent." (PMID 30581413, 2018). "Thus, CRP can be used as an indicator of infection, alongside a body temperature of more than 38.2°C." (PMID 29706967, 2018). "Additionally, previous research has suggested that while the basal level of CRP in cirrhotic patients is higher than in non cirrhotic patients, the degree of increase in CRP is less when liver function is impaired during infection." (PMID 30097024, 2018). "We conclude that AF hs-CRP is not feasible in assessing the risk of post-cesarean inflammation or infection." (PMID 29686267, 2018). "Although our results showed the existence of infection did not affect the prognostic significance of scoring systems, we could not exclude the possibility of other confounding effects that deranged CRP or albumin levels during infection may produce." (PMID 30367618, 2018). "The purpose of this study was to explore the diagnostic accuracy of CRP and procalcitonin in predicting presence or absence of each of the three major infections in seriously ill, HIV-infected inpatients." (PMID 30107791, 2018). "Finally, there was a significant correlation between low levels of C-reactive protein (CRP) and in vitro biofilm-forming capacity in S. epidermidis isolates from neonate blood infection." (PMID 29541068, 2018). "In addition, measuring CRP levels can help to screen both infections and inflammatory diseases; also, dynamic serial measurement of CRP has been widely used to help therapeutic decision making." (PMID 29780224, 2018). "However, no studies to date have examined the effects of repeated exposure to common infections on circulating IL-6 and CRP levels in children, which are typical markers of chronic, low-grade systemic inflammation." (PMID 29198208, 2018). "It has been shown that CRP is a good marker for bacteremia (Bloodstream infection)." (PMID 28235076, 2017). "The NTFET worked with CRP concentrations in the range 10−4–102 μg/mL, which is broad enough to be used in several applications, such as the monitoring of cardiovascular diseases and wound inflammation/infection." (PMID 29257113, 2017). "The CRP is known as a marker for infections and inflammatory processes in human blood serum." (PMID 28720856, 2017).
infection (continued). "There are important limitations to consider when using conventional diagnostic markers, such as blood cultures and inflammatory markers (i.e., C-reactive protein [CRP]), for patients with a clinical suspicion of infection, particularly in regard to suboptimal sensitivity and specificity." (PMID 28114931, 2017). "C-reactive protein (CRP) concentrations rise in response to tissue injury or infection." (PMID 28112148, 2017). "Furthermore, the data from the present study revealed that the delayed onset of an infection and persistent high CRP blood levels during therapy correlate negatively with the healing of a postoperative infection." (PMID 28592300, 2017). "C-reactive protein is a marker of acute inflammation and is associated with non-specific inflammatory responses by the human body to infection or trauma." (PMID 29201568, 2017). "When the data from just low– and medium–infection-burden countries (United States, Republic of Georgia, Mexico, and Colombia) were considered, the prevalence of an elevated CRP concentration in WRA (median: 24.3%) appeared to be higher than that in PSC (median: 11.7%)." (PMID 29070567, 2017). "Elevated CRP is a natural part of the inflammatory response to surgery, but may also be raised in infection, and can be an indicator of anastomotic leak." (PMID 28622070, 2017). "WCC and CRP were significantly increased in patients with a co-existing infection." (PMID 28158976, 2017). "PCT was superior to CRP in the diagnosis of infection during the study period." (PMID 28704503, 2017). "As a marker of infection the sensitivity of CRP has (at >8.7 mg/dL) been reported at 93.4%." (PMID 29104224, 2017). "A current infection was excluded by physical examination and measurement of C-reactive protein." (PMID 29201026, 2017). "The CRP was significantly higher in older dogs on Day 0, which could reflect the chronicity of the infection." (PMID 29143686, 2017). "CRP is a prominent clinical marker of infections and inflammatory disease." (PMID 28839172, 2017). "However, the persistence of systemic inflammation renders the prediction of infection challenging after trauma, as illustrated for example with the study of C-reactive protein." (PMID 29178941, 2017). "Importantly, the increases in liver and first-dose parameters, including CRP, a marker of infection and inflammatory processes, in response to blinatumomab were transient and reversible, and did not result in treatment interruptions or discontinuations." (PMID 28533941, 2017). "Thus, further investigation is needed in the surgical setting, and also to compare the accuracy and cost-effectiveness of PCT with other infection markers such as CRP." (PMID 28114931, 2017). "The level of infection with periodontal pathogens is positively correlated with CRP level." (PMID 28143450, 2017). "CRP is an acute phase protein, which is synthesized by the liver and released into the bloodstream within several hours after tissue injury, being able to reflect infection or an inflammatory status." (PMID 28209200, 2017). "Due to inflammation, it may be difficult to diagnose infection when it occurs, but measurement of C-reactive protein could facilitate this diagnosis." (PMID 28226029, 2017). "PCT showed no significant greater diagnostic utility over WCC or CRP for ability to distinguish between those patients with pleural malignancy and co-existing infection and those without co-existing infection." (PMID 28158976, 2017). "In daily routine, CRP is widely used as marker for inflammation, infection and tissue damage." (PMID 28514756, 2017). "The CRP, as a preoperative parameter, provided more accuracy in diagnosing delayed infections." (PMID 28841913, 2017). "Additionally, inflammatory syndrome was less pronounced (CRP: 76 vs. 147 mg/L; p = 0.02), with CRP <10 mg/L in 20% of CoNS infection cases versus CRP >10 mg/L in all SA infection cases." (PMID 29029624, 2017).
infection (continued). "Infections both raise and lower CRP concentrations in pregnant and lactating mothers." (PMID 28571565, 2017). "At the time of surgery, 29 (83%) and 27 (77%) patients in the bicarbonate and control groups, respectively, had active infection with a positive blood culture, leukocytosis (>10,800/μl), fever (temperature >38 °C), or elevated C-reactive protein (>8 mg/l) (P = 0.550)." (PMID 28057030, 2017). "CRP protein is significantly increased in the presence of infection and inflammation." (PMID 29404372, 2017). "Infection with either virus resulted in higher blood C-reactive protein (CRP)." (PMID 28553293, 2017). "CRP is a well-known soluble pattern recognition molecule that responds to infections." (PMID 28571565, 2017). "CRP in addition to WBC count is the most widely used parameter for diagnosis of infection." (PMID 28401944, 2017). "Besides the clinical aspects, the diagnosis of infection is supported by laboratory blood tests such as C-reactive protein (CRP), erythrocyte sedimentation rate (ESR), and peripheral leukocyte count." (PMID 27704194, 2017). "The standard practice for evaluating suspected infection included clinical assessment, culture sensitivities, antimicrobial optimization, and traditional biomarkers such as leukocyte count, bandemia, and C-reactive protein (CRP)." (PMID 29164170, 2017). "Patients with active infection or C-reactive protein > 20 mg/L were excluded." (PMID 29092739, 2017). "Plasma CRP level may dramatically increase by up to 10,000-fold at the time of acute responses to severe tissue damage or serious infection." (PMID 28706007, 2017). "Therefore, fast reacting biomarkers of infection have been used for almost 50 years to help the clinician, of which C-reactive protein (CRP) and procalcitonin (PCT) are the most often used and studied." (PMID 27597981, 2016). "Evaluation of these factors may also improve the interpretation of CRP as a biomarker for infection in the neonate." (PMID 26900695, 2016). "Smooth muscles and cardiomyocytes as well as infection parameters, such as CRP, IL-6, and procalcitonin, could be further examined to rule out effects on these tissues." (PMID 28050282, 2016). "CRP seemed to be of greater value than WBC in predicting the presence of a deep infection focus." (PMID 27182730, 2016). "Furthermore, the CRP level was higher among patients with a deep infection focus already on the day of the positive blood culture and at 2 weeks compared to patients in whom a deep infection focus was not verified." (PMID 27182730, 2016). "Therefore, the present study focused on the prediction of MIAC and HCA using a non-invasive approach, which involved the determination of a classical marker of infection, maternal serum CRP." (PMID 26942752, 2016). "However, we adjusted the statistical models with plasma CRP concentrations as a marker of recent infection." (PMID 27537051, 2016). "However, given the minimal systemic inflammatory response despite significant infection it remains to be seen if CRP is a useful marker of IA in CGD." (PMID 29376932, 2016). "Although some of them (CRP, procalcitonin) are routinely used in clinical practice to assess the responsiveness of antimicrobial therapy, their role in assessing the severity of infection and predicting clinical outcomes is limited." (PMID 27071911, 2016). "Point-of-care blood C-reactive protein (CRP) testing has diagnostic value in helping clinicians rule out the possibility of serious infection." (PMID 27716201, 2016). "The CRP level rose initially after the infection and waxed and waned for another 2 to 3 days." (PMID 27556404, 2016). "Both absolute values and kinetics of C-reactive protein are poor indicators of infection; furthermore, conventional indicators of infection such as white cell count and body temperature have limited use for predicting infection in the ICU." (PMID 27597981, 2016). "SF should be measured with CRP, to identify if raised SF is due to infection." (PMID 26891320, 2016).
infection (continued). "To evaluate the infection in the staphylococcal osteomyelitis model, we measured the serum interleukin-6 (IL-6) and C-reactive protein (CRP) in retro-orbital blood samples collected before surgery and on post-surgical days 1, 3, 7, and 14 from mice in the control and ionic-silver groups (n = 3, 3)." (PMID 26984477, 2016). "CRP is an acute phase protein and is released from the liver after stimulation by IL-6, underlining that CRP is not specific for infections." (PMID 26761003, 2016). "Also, the prediction rate of the initial DNI was significantly higher than that of initial serum WBC and CRP, which are commonly used markers for predicting inflammation and infection." (PMID 27682424, 2016). "CRP was seemed to be more sensitive to the presence of infection." (PMID 27227957, 2016). "In some cases, particularly for infection defined using CRP only, mapping the spatial random effect from the final model suggested that the factors included in the analysis may not have fully explained the variation observed." (PMID 27391972, 2016). "Clinically, CRP over 10 mg/L is suggestive of active inflammation or infection." (PMID 26959052, 2016). "The optimal CRP cut-off value for screening a deep infection focus was 108 mg/L at day 1 with sensitivity of 77% and specificity of 60%, 44 mg/L at day 7 with sensitivity of 68% and specificity of 67%, and 22 mg/L at day 14 with sensitivity of 59% and specificity of 76%." (PMID 27182730, 2016). "However, this increase in CRP is often misinterpreted as an infection and treatment is initiated—although bacterial cultures later are found to be negative and the patient dies." (PMID 27608043, 2016). "CRP is an acute phase protein used in clinical routine to detect ongoing inflammation or infection." (PMID 27653273, 2016). "Furthermore, the SAA level correlated directly with infection/ inflammatory markers (Leu and Neu number, ESR, CRP and Fb) depending on AS features, underlining its inflammatory potential." (PMID 27713770, 2016). "CRP values over 0.5 mg dL-1 are shown to be related to the infection-induced inflammatory response." (PMID 26863002, 2016). "The level of CRP increases in patients with trauma, inflammation and infection." (PMID 27347881, 2016). "PCT and CRP have been recognized as biomarkers with wide ranges in the short course of infection." (PMID 25894539, 2015). "Of note, multivariate Cox regression analyses, including markers of inflammation/infection (CRP, WBC), hepatic (bilirubin, INR) and renal (creatinine) function at day 3, revealed that OPN represents an independent significant prognostic parameter also for overall survival." (PMID 26111529, 2015). "Taken together, our study and previous studies suggest that the CRP may be a surrogate marker for the early identification of infection in hospitalized cirrhotic patients." (PMID 26498833, 2015). "CRP levels reflect the severity of tissue injury and infection." (PMID 25780458, 2015). "This discrepancy might be due to the fact that the present study excluded smokers, diabetics and patients with acute inflammation or infection having a CRP value above 20 mg/L." (PMID 25830914, 2015). "Therefore, NLR can be a helpful marker for identifying infection in hospitalized cirrhotic patients in addition to CRP." (PMID 26498833, 2015). "WBC and CRP levels are common markers of infection or inflammation." (PMID 26000296, 2015). "C-reactive protein estimation is also done as it is one of the early findings in infection." (PMID 25688311, 2015). "Later phase infection-inflammation conditions also enhance interaction between membrane GPCR43-associated M-ficolin and CRP, thus blocking M-ficolin binding of PAMPs and curtailing GPCR43-mediated IL-8 production, and allowing the restoration of homeostasis upon infection and injury." (PMID 25642836, 2015).
infection (continued). "Their elevation could represent a prodromal immunologic response to nascent infection or an inflammatory milieu characterized by CRP and IP-10 elevations that is ripe for reactivation of TB." (PMID 25719208, 2015). "However, several findings have been reported more frequently in patients with infection, including shaking chills, neutrophilic leucocytosis, and high CRP." (PMID 26798529, 2015). "In addition to clearing infection, CRP plays a regulatory role in inflammation and atherosclerotic thrombosis." (PMID 25889630, 2015). "In clinical settings, some cases of infection can be misdiagnosed because of a low CRP level." (PMID 25894539, 2015). "Similarly, the cutoff value for maternal ferritin level was set at 15 ng/mL for those mothers who were not reactive to CRP test and 30 ng/mL for those mothers who were reactive to CRP test in order to balance the effect of infection as recommended by the WHO." (PMID 25734012, 2015). "The lack of association between serum ferritin and infection-related mortality in the multivariate analysis including CRP, albumin and several comorbidities indicated that serum ferritin acts not only as iron storage but as acute phase reactant." (PMID 26599216, 2015). "As the clinical picture may be unclear, elevation of the erythrocyte sedimentation rate (ESR) and C-reactive protein (CRP) may be a guide to hip aspiration to exclude infection, which provides the opportunity for joint fluid metal ion analysis." (PMID 25954757, 2015). "In this NHANES cohort, at least 25% of women had CRP > 5 mg/L, and in such groups who are more prone to inflammation and infection, correcting for CRP may be more important." (PMID 25903453, 2015). "As the level of C-reactive protein (CRP) increases markedly in response to infection, and the magnitude of the increase may correlate with the severity of the infection, the prognostic value of CRP levels has been investigated in many diseases." (PMID 26158725, 2015). "Eliminating values over 3 mg/l restricts our understanding of CRP variation during the ovarian cycle by disregarding the normal function of inflammation, which is to increase dramatically but transiently in response to infection or wound healing." (PMID 26675298, 2015). "In the presence of severe infection or inflammation, CRP can rise above 500 mg/L." (PMID 26672961, 2015). "Similar to nIgG:ficolin complexes, infection-inflammation conditions significantly increase interaction between the acute phase protein C-reactive protein (CRP) and L-ficolin, leading to a stronger classical- and lectin-mediated complement response against Pseudomonas aeruginosa." (PMID 25642836, 2015). "CRP was considered to be an important marker for differential diagnosis such as infection." (PMID 26643853, 2015). "However, the traditional inflammatory markers, especially CRP, are essential to monitor the course of infection." (PMID 25987902, 2015). "Erythrocyte sedimentation rate and C-reactive protein levels may be normal or could be elevated in about 50% of cases suggesting an active infection." (PMID 26290668, 2015). "The use of CRP especially in OOH services is high and may reflect an acquired practice to routinely perform a CRP test when the patient has fever or an infection." (PMID 26585447, 2015). "However, studies have found CRP to have a sensitivity of 91–93 % but a sensitivity of just 83–86 % in connection with infections." (PMID 25987902, 2015). "Moreover, our exclusion of data from subjects with high levels of CRP would have minimized the influence of intercurrent infection." (PMID 26251920, 2015). "In conclusion, our study suggested that the high serum PCT levels, like CRP is also associated with inflammatory gouty arthritis without infection susceptibility in southern Chinese Han population." (PMID 26182343, 2015). "This might be in part due to the supportive therapy, but CRP-values were also lower following three days of treatment indicating an effect on the infection." (PMID 26700635, 2015).